FGFR2 (fibroblast growth factor receptor 2)
Diseases named in the same sentence as FGFR2 in open-access papers (continued):
Sharing a sentence is not in itself a finding about the gene and the disease.
endometrial cancer (continued). "As the FGFR small-molecule inhibitor PD173074 diminishes survival and anchorage-independent growth by endometrial cancer cell lines expressing activating FGFR2 mutations." (PMID 33193890, 2020). "Recently NRG Oncology/Gynecologic Oncology Group study showed association of FGFR2 mutations with poor outcomes in endometrial cancer." (PMID 32111026, 2020). "A potential therapeutic benefit of combining an FGFR inhibitor PD173074 with the standard chemotherapeutic agents (e.g., paclitaxel or doxorubicin) was also observed for patients with endometrial cancer, especially with FGFR2-mutation-positive tumors." (PMID 31948066, 2020). "Loss of function mutations in FGFR2 gene contributed to melanoma progression, whilst gain of function alterations were reported to promote growth of endometrial carcinoma." (PMID 32971804, 2020). "To investigate mechanisms of acquired resistance to FGFR inhibitors, we adopted endometrial cancer cell line models, with two cell lines that harbor FGFR2 activating mutations, MFE-296 and AN3CA cells, and one that expresses wild-type FGFR2, Ishikawa cells." (PMID 29490281, 2018). "Mutations are present in 12% of endometrial carcinomas and FGFR2 mutant endometrial cancer cell lines are highly sensitive to FGFR tyrosine kinase inhibitors, implicating FGFR2 as an innovative therapeutic target in endometrial carcinoma." (PMID 28030802, 2017). "FP-1039 mediated tumor inhibition occurs more specifically in FGFR1-amplified lung cancer and FGFR2-mutated endometrial cancer." (PMID 27051190, 2016). "It was recently reported that FGFR aberrations were found in 7.1% of cancers, while FGFR2 activating mutations were found in 10-16% of primary endometrial cancers." (PMID 26824324, 2016). "For instance, mutations in FGFR3 are frequent in bladder carcinoma, and FGFR2 mutations in endometrial cancer, melanoma, and gastric tumors." (PMID 26224133, 2015). "Regarding the mutation of FGFR2, somatic mutations of FGFR2 have been found in 12% (15/122) of endometrial carcinomas and these FGFR2 mutations have an oncogenic property that confers hypersensitivity to FGFR inhibitors." (PMID 23426935, 2013). "In endometrial cancer cells harboring activated mutations of FGFR2, knockdown of FGFR2 using short hairpin (sh) RNA or treatment with a pan-FGFR inhibitor, PD173074, caused cell cycle arrest and cell death." (PMID 22701813, 2012). "This cohort also allows the assessment of FGFR2 mutations on endometrial cancer specific survival as well as overall survival, given the extensive clinical annotation of these samples." (PMID 22383975, 2012). "Among the included genes and mutations, we have identified and validated KRAS, PIK3CA and FGFR2 to be the most frequently mutated oncogenes in endometrial cancer." (PMID 23300780, 2012). "We, and others, have previously linked these mutations to endometrial cancer, through increased tumor cell survival and anchoring independent growth in endometrial cancer cell lines, and indicated the potential for FGFR2 inhibitors in mutated cell lines." (PMID 23300780, 2012). "Gene amplification or missense mutations of FGFR2 occur in gastric, lung, breast, ovarian, and endometrial cancers and melanomas." (PMID 22701813, 2012). "It has also been reported that FGFR2 inhibitors induce cell death in endometrial cancer cells despite PTEN inactivating mutations." (PMID 23300780, 2012). "The frequency of FGFR2 mutations detected in the present OncoMap screen of 10.4% is in concordance with our previous findings from 122 endometrial cancer patients from the same region, finding FGFR2 to be mutated in 12.3%." (PMID 23300780, 2012).
endometrial cancer (continued). "Our previous screening of a smaller number of endometrial cancer patients identified somatic mutations in FGFR2, KRAS, PIK3CA, PTEN, PT53 and CTNNB1." (PMID 23300780, 2012). "Investigation of these agents in endometrial cancer patients with activating FGFR2 mutations is warranted." (PMID 20148071, 2010). "In vitro studies have shown that endometrial cancer cell lines with activating FGFR2 mutations are selectively sensitive to a pan-FGFR inhibitor, PD173074." (PMID 20148071, 2010). "A large-scale functional study identified 71 newly confirmed oncogenic variants among 160 FGFR mutations; FGFR2 mutations in endometrial cancer significantly correlate with molecular subtypes, showing markedly elevated frequency in microsatellite instability-high (MSI-H) tumors." (PMID 41514604, 2025). "In addition, molecular features such as microsatellite instability (MSI), mutations in proto-oncogene genes like PTEN and k-RAS, and cell growth induction mutations such as FGFR2 can be used to identify endometrial carcinoma." (PMID 40958876, 2025). "FGFR2 mutations render endometrial cancer cells more sensitive to FGF7 stimulation." (PMID 37165578, 2023). "•FGFR2 mutations are related with deep myometrial invasion in endometrial carcinoma." (PMID 33450701, 2021). "Recently, several independent studies have identified FGFR2 mutations in endometrial cancer 44-46." (PMID 33193890, 2020). "Mutations in FGFR2 are found (10–12%) in the endometrial cancers." (PMID 31583159, 2019). "Furthermore, activating mutations of FGFR2 have been identified in approximately 10% of endometrial cancers, and inhibition of activated mutations of FGFR2 induced apoptosis and growth inhibition of endometrial carcinoma cells." (PMID 22701813, 2012). "In conclusion, our mutation analysis of four oncogenes frequently mutated in the endometrioid histology of endometrial cancer revealed that mutated FGFR2 was associated with shorter disease free progression and this was significant in patients diagnosed with early stage disease." (PMID 22383975, 2012). "SNPs of intron 2 in FGFR2 are associated with an increased risk of breast and endometrial cancers." (PMID 22701813, 2012). "Activating FGFR2 mutation could be an important therapeutic target for endometrial cancers." (PMID 33193890, 2020). "Although transcriptional signature pattern according to histologic grade did not identify any distinct subgroups linking any of the mutations to phenotype, PIK3CA, KRAS and FGFR2 mutations may still be of relevance for targeting novel therapeutics in endometrial cancer." (PMID 23300780, 2012). "Our finding that FGFR2 mutation is an independent prognostic marker in patients with early stage endometrioid endometrial cancer suggests that FGFR2 mutation testing could ultimately prove useful in the management of endometrial cancer." (PMID 22383975, 2012). "On the opposite end, two CDNs with imax > 20 are observed in only one cancer type (EGFR: T2573 in lung and FGFR2: C755 in endometrium cancer)." (PMID 39688957, 2024). "In endometrial cancer, FGFR2 has been reported to be activated in an autocrine manner, which activates AKT signaling and its downstream hairy and enhancer of split‐1 (HES1), thereby promoting tumor cell proliferation." (PMID 37750089, 2023). "FGFR2 mutations often present simultaneously with PTEN mutations, in about 77% of primary endometrial cancers." (PMID 37465112, 2023). "FGFR2 SVs/REs also commonly occurred in endometrial cancer (SVs: 804/11 101, 7.2%; REs: 23/11 101, 0.2%)." (PMID 36462464, 2022).
endometrial cancer (continued). "According to The Cancer Genome Atlas (TCGA) data reported in Nature in 2013, the most frequently altered FGFR gene in endometrial cancers was FGFR2, with 12.5% of sequenced samples (n=248 samples) harboring alterations in this gene." (PMID 33193890, 2020). "In a clinical study in FGFR2-mutant or wild-type endometrial cancer patients treated with dovitinib, the RR in the FGFR2 mutant group was 5% (11% for all patients); only 1/22 FGFR2 mutant patients achieved a partial response (PR)." (PMID 32962091, 2020). "In a phase I study of erdafinitib, responses were observed in a patient with endometrial cancer (FGFR2 fusion) and glioblastoma (FGFR3 fusion)." (PMID 35582593, 2019). "Most molecular studies in endometrial cancer have focused on the most common form, uterine endometrioid carcinoma (UEC), which is primarily driven by PTEN loss and mutations in FGFR2, ARID1A, CTNNB1, PIK3CA, PIK2R1, and KRAS." (PMID 26170901, 2015). "The fact that FGFR2 and KRAS mutations are mutually exclusive in endometrial cancers points to the importance of activation of the ERK pathway." (PMID 23941783, 2013). "Mutations in multiple oncogenes including KRAS, CTNNB1, PIK3CA and FGFR2 have been identified in endometrial cancer." (PMID 22383975, 2012). "Our results emphasize the potential for targeting FGFR2, KRAS and PIK3CA mutations in endometrial cancer for development of novel therapeutic strategies." (PMID 23300780, 2012). "FGFR2-IIIc also plays a prognostic role in endometrial cancer." (PMID 41584352, 2026). "The treatment of FGFR2-driven MFE-296 endometrial cancer cells with the FGFR inhibitor PD173074 was also shown to decrease H3K4me3 and H3K27ac at the PHLDA1 locus, and levels of PHLDA1 in this model were also found to be regulated by a PKC/MAPK-mediated pathway." (PMID 37047202, 2023). "FGFR2 mutations occur most frequently in endometrial cancer (EC) (10%–12%); however, not all FGFR2 mutations are effective targets." (PMID 37493315, 2023). "Taken together, our results support the hypothesis that FGFR2 crosstalk has a dual role in the endometrium, by regulating cell proliferation in normal endometrium, but acting as an oncogene in endometrial carcinoma." (PMID 37165578, 2023). "In addition, FGFR2 is highly expressed in various solid tumors, including gastric and endometrial cancers, indicating that FGFR2 is a potential biomarker of human cancers." (PMID 35311468, 2022). "FGFR2 plays a critical role in promoting carcinogenesis in various cancers, such as gastric cancer, cholangiocarcinoma, colorectal cancer, and endometrial cancer." (PMID 35311468, 2022). "Recent work on endometrial cancer showed that FGFR inhibitors (Infigratinib, AZD4547 and PD173074) caused mitochondrial depolarisation, cytochrome c release and impaired mitochondrial respiration in two FGFR2-mutant endometrial cancer cell lines (AN3CA and JHUEM2)." (PMID 34830836, 2021). "Decreased cancer-specific survival is also seen in a multi-institutional cohort of over 950 endometrial cancer patients with somatic FGFR2 mutations, irrespective of stage 59." (PMID 33193890, 2020). "Noticeably, co-treatment of FGFR2 and mTOR has a synergistic effect on the growth of endometrial cancer cell lines bearing an activating FGFR2 mutation, irrespective of PTEN status." (PMID 33193890, 2020). "Somatic mutations in FGFR1, FGFR2, FGFR3, and FGFR4 genes are reported in endometrial cancer." (PMID 33193890, 2020). "Similarly, selective sensitivity of FGFR2-mutant endometrial cancer to FGFR inhibitors was demonstrated in in vitro and in vivo models." (PMID 30326595, 2018). "A previous study of endometrial cancer suggested FGFR2 to be a tumor suppressor protein." (PMID 25794154, 2015).
endometrial cancer (continued). "Amplification or mutation of fibroblast growth factor receptor (FGFR) has been reported in endometrial cancers with a frequency of 10% and FGFR2 may represent a novel molecular target for the treatment of endometrial cancer." (PMID 26244161, 2015). "Indeed, our reports encourage the perspective investigation of combination of everolimus along with hormone-therapy in pre-treated FGFR2+ recurrent endometrial cancer patients." (PMID 26244161, 2015). "The targeting of FGFR2 is a possible treatment strategy for endometrial carcinoma." (PMID 26366417, 2015). "In endometrial cancer dovitinib treatment effect seemed independent of FGFR2 mutation status." (PMID 37647320, 2023). "Inhibition of FGFR family members by ponatinib has been demonstrated in preclinical models of endometrial cancers with FGFR2 mutations, bladder cancers with FGFR3 mutations, as well as breast, lung, and colon cancer cell lines harboring amplification of the FGFR1 or FGFR2 gene." (PMID 24124571, 2013). "Given that dovitinib may exert its anticancer effects either by directly targeting FGFRs or regulators of angiogenesis, endometrial cancer patients with or without FGFR2 mutations are separately enrolled in a clinical to prove its mechanisms of functions." (PMID 23900974, 2013). "Consistently, in endometrial cancer, research utilizing patient-derived xenograft (PDX) and organoid (PDXO) models has demonstrated that tumors with high FGFR2-IIIc expression exhibit heightened sensitivity to FGFR inhibitors such as BGJ398 and pemigatinib." (PMID 41584352, 2026). "All patients demonstrating a PR had FGFR2 or FGFR3 translocations, and tumour types were reported as glioblastoma, UC, and endometrial cancer." (PMID 28070720, 2017). "The present study aimed to investigate the influence of FGFR-2 on the epithelial–mesenchymal transition (EMT) and whether it can lead to endometrial cancer dedifferentiation." (PMID 36143062, 2022). "In addition, oncogene, fibroblast growth factor receptor 2 (FGFR2), P13KCA, and epidermal growth factor receptor (EGFR) are also playing a necessary role in endometrial cancer." (PMID 31583159, 2019). "We can speculate that the pattern of mutual exclusivity of FGFR2 and KRAS suggests that the role of these two genes in endometrial cancer initiation is likely to be through activation of the MAPK signaling pathway." (PMID 22383975, 2012). "The reason for the disparate results between lung and endometrial cancer models is unknown but could be due to higher expression of Mcl‐1 in lung cancers and/or differences in other prosurvival/pro‐apoptotic proteins regulated by FGFR1 and FGFR2." (PMID 30537101, 2019). "Additionally, ERK activation is seen in endometrial cancers without mutations in KRAS and FGFR2 (and our unpublished data)." (PMID 23941783, 2013). "However, several ongoing clinical trials aim at exploiting targets supported by recent comprehensive molecular profiling of primary endometrial carcinoma lesion, dominated by trials targeting the phosphatidylinositol 3-kinase (PI3K)/AKT/mammalian target of rapamycin (mTOR) or FGFR2." (PMID 23300780, 2012).
Crouzon syndrome (63 papers, 2010 to 2026). "Genetic conditions caused by pathogenic variants in FGFR2, such as Apert, Pfeiffer, and Crouzon syndromes, result in calvarial deformities due to premature suture fusion and a persistently open anterior fontanelle (AF)." (PMID 39775862, 2025). "Germline and somatic mosaicism for FGFR2 mutation inthe mother of a child with Crouzon syndrome: implications for genetictesting in “paternal age-effect” syndromes." (PMID 40995454, 2025). "The husband’s father had a milder form of Crouzon syndrome and the pathogenic variant of the FGFR2 gene was in a mosaic form." (PMID 40995454, 2025). "In this study, a mouse model for Crouzon syndrome was used to identify the specific effects of FGFR2 mutation on calvarial bone microstructure." (PMID 39096036, 2024). "As mentioned, the p.C342Y mutation in the FGFR2 is the most common coding mutation causing Crouzon syndrome." (PMID 39096036, 2024). "Crouzon syndrome, caused by FGFR2 mutations, leads to premature cranial suture fusion and abnormal head shapes." (PMID 39096036, 2024). "The index patient also suffers from Crouzon syndrome caused by a heterozygous c.833G>T;p.(Cys278Phe) pathogenic variant of the FGFR2 gene (NM_022970)." (PMID 38820174, 2024). "Crouzon syndrome is a congenital craniofacial disorder caused by mutations in the Fibroblast Growth Factor Receptor 2 (FGFR2)." (PMID 39096036, 2024). "Our current case demonstrates that Crouzon syndrome patients can carry the FGFR2 gene c.G812T:p.G271V mutation, extraocular muscle fibrosis, and large-angle exotropia." (PMID 36755349, 2023). "Our case demonstrates that patients with Crouzon syndrome can show an FGFR2 gene c.G812T:p.G271V mutation along with clinical symptoms consisting of lateral rectus muscle fiber degeneration, exotropia, exophthalmos, and a pointed head deformity." (PMID 36755349, 2023). "It has been well established that many different mutations in the FGFR2 gene are associated with Crouzon syndrome." (PMID 36755349, 2023). "This case demonstrates that Crouzon syndrome patients can show an FGFR2 gene c.G812T:p.G271V mutation and display clinical symptoms such as extraocular muscle fibrosis, exotropia, exophthalmos, and a pointed head deformity." (PMID 36755349, 2023). "Cases 3 and 4 had Crouzon syndrome, which is a FGFR2-related disorder associating cranio-facial malformations, hydrocephalus, and cervical spine anomalies." (PMID 37959181, 2023). "This case demonstrates that Crouzon syndrome patients can show a fibroblast growth factor receptor 2 (FGFR2) gene c.G812T:p.G271V mutation and display clinical symptoms such as extraocular muscle fibrosis, exotropia, exophthalmos, and a pointed head deformity." (PMID 36755349, 2023). "Most FGFR2 mutations are located in the Ig-III domain that has been proven to be a genetic contributor to Crouzon syndrome through the activation of one or more FGF/FGFR downstream signaling pathway(s)." (PMID 36231091, 2022). "The fibroblast growth factor receptor-2 (FGFR-2) gene mutation that leads to early suture line closure is the basis for the development of Crouzon's syndrome." (PMID 36457643, 2022). "In this study, we fully investigated the FGFR2 mutation p.Cys342Arg detected in two Chinese Crouzon syndrome patients and revealed the novel mechanism whereby FGFR2 p.Cys342Arg -AMPK-Erk1/2 axis regulates osteogenesis by enhancing the mitochondrial metabolism." (PMID 36231091, 2022). "Mice carrying two additional gain-of-function Fgfr2 mutations that can be found in humans with Crouzon syndrome – Fgfr2C342Y/+ (Cys342Tyr) and Fgfr2W290R/+ – have phenotypes that recapitulate the clinical characteristics of this syndrome." (PMID 35451466, 2022). "We report an FGFR2 gene variant in a mother and daughter who present with different clinical features of Crouzon syndrome." (PMID 35885943, 2022).